ENSG00000287908 (novel protein)
Gene: Protein-coding gene on chromosome 12 (57,615,280 to 57,626,125, forward strand). Ensembl gene ENSG00000287908.
Genetic constraint (gnomAD): Missense variants: 289 observed, 313.27 expected, observed/expected ratio (o/e) 0.92, 90% interval 0.84 to 1.02. Synonymous variants: 127 observed, 124.86 expected, observed/expected ratio (o/e) 1.02, 90% interval 0.88 to 1.18.